DDX41 (DEAD-box helicase 41)
Diseases named in the same sentence as DDX41 in open-access papers (continued):
Sharing a sentence is not in itself a finding about the gene and the disease.
myeloid leukemia (1 paper, 2025). A clonal proliferation of myeloid cells and their precursors in the bone marrow, peripheral blood, and spleen. "Other known myeloid leukemia predisposition genes, including DDX41 (P = 3.68e−4, β = 0.115770) and RUNX1 (P = 3.99e−4, β = 0.176099), were identified at a lower significance level than seen for CHEK2 pLoF variants." (PMID 40335619, 2025).
ovarian carcinoma (1 paper, 2024). A malignant neoplasm originating from the surface ovarian epithelium. "Instead of targeting DDX41 itself, we can target DDX41's SL partner, analogous to the case where PARP-1 inhibitors are used to treat BRCA1/2-mutated breast and ovarian cancer patients." (PMID 38348889, 2024).
parasitic infections (1 paper, 2025). "Infection of BTK knockout mice with Plasmodium yoelii led to higher parasitemia and lower survival as compared to WT mice, suggesting activation of DDX41 may be crucial for sensing of Plasmodium DNA." (PMID 39620586, 2025).
systemic lupus erythematosus (1 paper, 2021). An autoimmune multi-organ disease typically associated with vasculopathy and autoantibody production. "TRIM21 (known as Ro52), an autoantigen in patients with SLE (systemic lupus erythematosus), targets DDX41 for degradation." (PMID 33670221, 2021).
tumor (24 papers, 2017 to 2025). "Dysfunctional DDX41 predisposes individuals to neoplasia, mainly of myeloid origin, although the pathogenic mechanisms are not fully understood." (PMID 40725152, 2025). "The majority of germline mutations are frameshift mutations suggesting loss of function with DDX41 acting as a tumor suppressor, and there is a common somatic missense mutation found in a majority of germline mutated tumors." (PMID 36338673, 2022). "Early reports indicated germline DDX41 mutations are associated with high grade neoplasms and diploid karyotype with relatively poor outcomes, although more recent reports show more encouraging trends in outcomes." (PMID 33585199, 2020). "DDX41 defects lead to loss of tumor suppressor function due to altered pre-mRNA splicing and RNA processing." (PMID 27502187, 2017). "It was concluded that DDX41 defects lead to loss of tumor suppressor function due to altered pre-mRNA splicing and RNA processing." (PMID 27502187, 2017). "Although the mechanisms underlying DDX41’s tumor suppressor function have been elucidated to some extent, the structural and functional consequences of pathogenic variants of DDX41 remain unclear." (PMID 39185415, 2024). "Thus, a loss of tumor suppressive function of G3BP1 or DDX41 may lead to leukemic evolution in del(5q)." (PMID 28031539, 2017). "The compromised tumor suppression observed in patients with DDX41 variants may be related to disruption of pre-mRNA splicing, RNA processing, small nucleolar RNA processing, or ribosome biogenesis, implicating the normal function of DDX41 in these crucial biological processes." (PMID 39453476, 2024). "Our data demonstrated that the effect of cell cycle inhibitors on SASP expression was boosted significantly in hypoxic tumor due to the upsurge of HIF-regulated DDX41." (PMID 39388278, 2024). "Dead box helicase 41 (DDX41) is a tumor suppressor that is conserved in D. melanogaster, C. elegans, D. rerio, and plants, and is considered essential for cell growth and viability." (PMID 34916496, 2021). "In xenograft experiments with cell lines in which DDX41 was knocked down, they observed accelerated tumor growth compared to mock transduced cells, implying DDX41 functioning as a tumor suppressor." (PMID 27502187, 2017). "This suggested a potential tumor suppressor role for DDX41 in some solid tumors." (PMID 39185415, 2024). "Moreover, the regulation of immune-associated genes in the DDX41-overexpressing HeLa cells correlated with findings from the CESC dataset analysis, indicating a potential link between DDX41 and tumor immunity." (PMID 39185415, 2024). "Germline variants in genes such as CEBPA, DDX41, RUNX1, ETV6 and GATA2 should be considered in patients when mutations in these genes are seen in tumor sequencing tests, especially when the mutations are biallelic or consistent with their presence in the germline." (PMID 36338673, 2022). "Our results showed that DDX41 expression in human CRC was much higher than the control groups but the association with tumor stages was not identified." (PMID 31949493, 2020). "Added importance of structural investigation comes from the indication that DDX41 may function as a tumor suppressor, and could be a good therapeutic target for disease treatment." (PMID 27502187, 2017). "Furthermore, we separated tumor cells from mouse models and found that the DTIC+Rem group had lower protein levels of DDX41 and ZNF746 compared with the DTIC group." (PMID 39246323, 2024). "DDX41 (DEAD-Box Helicase 41) is a gene located on the 5q35.3 cytogenetic band and belongs to DEAD box proteins with a putative RNA helicase function, and it seems to be a tumor suppressor gene." (PMID 35885562, 2022). "The other tested DNA sensors (Rig-I, Cgas, Sting, Ddx41, Dhx9, Dhx36, Lrrfip1, Mre11) were expressed in the tumor cells but were not significantly upregulated after irradiation." (PMID 33202881, 2020).
hematologic malignancies (23 papers, 2018 to 2026). "DDX41 heterozygotes were prevalent in the population (1:576–870), with high likelihood to develop a hematological malignancy (1:19–1:39), and had an increased overall all-cause mortality." (PMID 39501104, 2025). "This study aims to investigate the frequency, spectrum, and clinical characteristics of DDX41 variants in Korean patients with hematologic malignancies, including the patterns of co-occurring somatic variants." (PMID 41303035, 2025). "This study investigated the frequency and spectrum of DDX41 variants in Korean patients with hematologic malignancies, and evaluated the characteristics of somatic variants co-occurring with germline DDX41 variants." (PMID 41303035, 2025). "DDX41 variants were identified in 34 of 716 patients (4.7%) with hematologic malignancies, including 33 patients (4.6%) with germline DDX41 variants and one with only a somatic DDX41 variant." (PMID 41303035, 2025). "In our study, germline DDX41 variants were detected in 4.6% of patients with hematologic malignancies, with higher prevalence in AML (6.2%) and MDS (11.1%)." (PMID 41303035, 2025). "This study investigated the frequency, spectrum, and clinical characteristics of DDX41 variants in Korean patients with hematologic malignancies, including the patterns of co-occurring somatic variants." (PMID 41303035, 2025). "In conclusion, we characterized the frequency, spectrum, and clinical features of DDX41 variants in Korean patients with hematologic malignancies." (PMID 41303035, 2025). "DDX41 mutations are linked to cancer predisposition syndrome characterized by increased susceptibility to hematological malignancies." (PMID 38350915, 2024). "Heterozygous germline mutations in DDX41 cause predisposition to hematologic malignancies with a 50% lifetime penetrance." (PMID 38937548, 2024). "Germline heterozygous mutations in DDX41 predispose individuals to hematologic malignancies in adulthood." (PMID 38937548, 2024). "Only about 30% of patients with germline DDX41 mutations have a family history of hematologic malignancy, but a familial series study showed high penetrant patterns in some families." (PMID 36672294, 2023). "More than half (74%) of these variants (germline = 33, somatic = 22) have been previously reported in a DDX41-mutated hematologic malignancy or were seen in more than one DDX41 mutated patient from this study cohort." (PMID 37434984, 2023). "We analyzed the prevalence and characteristics of DDX41 mutations in an unselected cohort of patients with hematological disorders to advance our understanding of this gene." (PMID 35844724, 2021). "It was reported that mutations in DEAD-box helicase 41 (DDX41) was also associated with blood disorders including MDS." (PMID 34638816, 2021). "Functional analysis of ddx41 in zebrafish embryos revealed that it was required for the expansion and differentiation of erythroid progenitors, and these results promoted the understanding of hematologic malignancies induced by mutations in DDX41." (PMID 34638816, 2021). "NGS panel testing, through multidisciplinary collaboration, provides a feasible mechanism to screen unselected hematologic malignancy patients for high likelihood of germline DDX41 mutations." (PMID 33585199, 2020). "Herein we describe the identification and characterization of patients with DDX41 germline mutations identified through the incorporation of DDX41 mutation testing in patients with hematologic malignancies." (PMID 33585199, 2020). "Regarding family history, 77% of patients evaluated for potential germline DDX41 mutation reported a family history of cancer and/or hematologic disorder." (PMID 33585199, 2020).
hematologic malignancies (continued). "DDX41 mutations have been identified in ~3% of inherited hematologic malignancies, and the defective DDX41 have been implicated in promoting exon skipping or exon retention in dozens of genes." (PMID 30463359, 2018). "Notably, heterozygotes for germline P/LP variants in GATA2, ETV6, and RUNX1 (both cohorts), and DDX41 (UKBB only) have significantly increased risk for developing hematological malignancies." (PMID 39501104, 2025). "Overall, understanding the molecular and cellular mechanisms of DDX41 could help develop novel therapeutic options for DDX41 mutation-related hematologic malignancies." (PMID 38348889, 2024). "DDX41 mutations are also associated with blood disorders, including macrocytosis." (PMID 36672294, 2023). "The specific risk for hematologic malignancies including MDS/AML conveyed by DDX41 mutations remains unclear." (PMID 36672294, 2023). "The similarity of germline CEBPA, DDX41 and RUNX1 mutations associated with haematological diseases warrants further study, such as the long time to follow-up with the family members." (PMID 35279121, 2022). "Here, we sought to analyze the genomic architecture, bone marrow morphology as well as immunophenotypes of patients with DDX41 mutated AML, MDS and MPN to explore possible genotype–phenotype correlations between individuals with these DDX41 related hematologic malignancies." (PMID 37434984, 2023). "More than half of these VUS (n =28) have been reported in association to DDX41 mutated hematologic malignancies, but were never characterized." (PMID 37434984, 2023). "Although solid tumors are sometimes found in patients with hematological malignancies and germline DDX41 variants, an association between DDX41 variants and onset of non-hematological maligancies has not been definitively shown." (PMID 36119490, 2022). "Dead-box helicase 41 (DDX41), a helicase, not only unwinds DNA-RNA hydrids but also activates the cGAMP synthase (cGAS)-Stimulator of Interferon Genes (STING) pathway in blood disorders." (PMID 40061014, 2025). "Recent studies have reported the role of several DHX9-like genes including DDX41, DDX3X, and DHX32 in hematological diseases." (PMID 37305700, 2023). "Our results demonstrate that MDS/AML cases harboring two DDX41 variants share specific clinicopathologic hallmarks that are not seen in other patients with monoallelic DDX41 related hematologic malignancies." (PMID 37434984, 2023).
cancer (18 papers, 2016 to 2026). A tumor composed of atypical neoplastic, often pleomorphic cells that invade other tissues. "To investigate the mechanism by which DDX41 suppression caused DNA replication stress with R-loop accumulation, we analyzed the Cancer Dependency Map (DepMap) dataset." (PMID 36229594, 2022). "Using patients’ data in The Cancer Genome Atlas, we have previously examined the expression of DDX41 in 24 different cancer types and found that DDX41 is up-regulated in most cancers." (PMID 38348889, 2024). "As DDX41 is overexpressed in multiple cancers, spliceosome inhibitors should benefit these patients, provided the functional interaction is conserved." (PMID 36761420, 2022). "Despite the relevance of DDX41 in cancer, the cellular and molecular functions of DDX41 remain poorly understood." (PMID 34916496, 2021). "Some of them are only overexpressed across human cancers, such as DDX27, DDX41 and DDX56, while most of them are both overexpressed and lost in different cancer types." (PMID 36761420, 2022). "Of note DDX41, which uniquely predisposes to MDS at the typical time of onset for sporadic MDS, does not have an earlier onset in the time to all cancer analysis performed for DiscovEHR." (PMID 39501104, 2025). "Interestingly, the direction of regulation of these oncogenes (DDX41-overexpressing HeLa vs. WT HeLa) was consistent with their regulation in the cervical and endocervical squamous cancer (CESC) dataset (normal vs. cancer)." (PMID 39185415, 2024). "Recent studies suggest that DNA sensors such as AIM2, TLR9, DHX9, DHX36 and adaptor STING may have roles in CRC development, and the other DNA sensors such as DDX41, DDX60, IFI16, and DAI participate in the development of other types of cancers." (PMID 31949493, 2020). "As for other genes involved in dsDNA/dsRNA/ssRNA sensing like CGAS, RIG-I, MAVS, DDX41, and IFI16, whose expression in either cancer cells or other cell types, were not significantly impacted by redox status of any cell types." (PMID 41378285, 2025).
infection (7 papers, 2018 to 2025). The state of being infected such as from the introduction of a foreign agent such as serum, vaccine, antigenic substance or organism. "DDX41 also triggers antiviral responses after infection with adenovirus, a DNA virus that replicates in the nucleus." (PMID 39185415, 2024). "Recent studies also suggest that DDX41 can sense DNA/RNA hybrids released from damaged mitochondria during infection by other RNA viruses." (PMID 39185415, 2024). "DDX41 was first studied because of its recognition of DNA or DNA/RNA hybrids generated during infection, triggering anti-viral and -bacteria immune responses." (PMID 39185415, 2024). "Although DDX41-knockout STING-A549 cells released comparable levels of mtDNA into the cytosol upon influenza virus infection, DDX41-knockout STING-A549 cells significantly reduced the IFN-β gene expression after infection with influenza virus or EMCV." (PMID 31604929, 2019). "Further, the biotin-tagged 45 bp interferon stimulatory DNA (ISD) coimmunoprecipitated with NS1 and DDX41 in cGAS-293FT cells after infection with WT PR8 influenza virus." (PMID 31604929, 2019). "Mice with complete knockout of Ddx41 in DCs showed 5-fold-higher infection than either wild-type mice or mice heterozygous for the DDX41 knockout allele in this cell type." (PMID 29871919, 2018). "Here, we show that DDX41 is a critical sensor of viral nucleic acids generated during reverse transcription and is required to control in vivo infection." (PMID 29871919, 2018). "However, the representation profile of DDX41 and lysine-tRNA ligase decreased and increased only in response to vaccination or infection, respectively." (PMID 32344637, 2020). "We also examined whether DDX41 expression in BMDMs or BMDCs was important to suppress long-term in vivo infection." (PMID 29871919, 2018). "To determine whether DDX41 and cGAS functioned in vivo to suppress infection, we subcutaneously inoculated the CD11cCre-DDX41 and cGas KO mice with MLV and measured infection levels in the draining lymph node; wild-type (Ddx41f/f mice without Cre) and Stinggt/gt mice served as controls." (PMID 29871919, 2018). "Although DDX41 recognizes cytosolic DNA and initiates the STING-TBK1-IRF3-IFN I signaling pathway, during infection with retroviruses such as MLV and HIV, DDX41 primarily senses the DNA/RNA hybrids generated during viral reverse transcription." (PMID 39185415, 2024). "In addition, the anti-dsDNA antibody coimmunoprecipitated with cGAS, DDX41, and TFAM in cGAS-293FT cells after infection with WT PR8 influenza virus." (PMID 31604929, 2019). "We thus compared infection levels between mice with a total lack of DDX41 due to full knockout of the gene in the specific compartment and mice with only one knockout allele and mice with no knockout of Ddx41." (PMID 29871919, 2018). "Infection levels in the CD11cCre-DDX41/cGAS siRNA group were not statistically different from those in the cGas KO/DDX41 siRNA group." (PMID 29871919, 2018). "This may explain why mice lacking DDX41 or cGAS show only 5-fold-higher infection than wild-type mice; even STING-deficient mice show only 10-fold-higher infection." (PMID 29871919, 2018). "Moreover, using mice with cell-type-specific knockout (KO) of DDX41, we show that dendritic cells (DCs) and not myeloid-derived cells are likely the major sentinel cell targets of in vivo infection." (PMID 29871919, 2018). "Although depletion of mtDNA did not change the expression levels of DDX41, RIG-I, MAVS, and STING, ρ0 HEK293FT cells significantly reduced the IFN-β gene expression after infection with ΔNS1 influenza virus." (PMID 31604929, 2019). "Proteins such as DEAD (Asp-Glu-Ala-Asp) box polypeptide 41 (DDX41) and Rac family small GTPase 2 were underrepresented or overrepresented, respectively, in response to vaccination but did not change in response to infection." (PMID 32344637, 2020).
infection (continued). "Thus, although DDX41 sensed MLV infection in macrophages in vitro and ex vivo, this response in vivo was not sufficient to control infection." (PMID 29871919, 2018).
genetic disorders (2 papers, 2021 to 2024). "The observed reductions in DDX41 stability, reduced IFN-I response, and transcriptome-wide RNA splicing changes highlight the intricate molecular mechanisms underlying this genetic disorder." (PMID 39453476, 2024). "This novel insight adds a layer of complexity to our understanding of DDX41’s multifaceted functions, emphasizing its significance in genetic disorders and the regulation of pivotal genes like periostin, thereby broadening our comprehension of its roles in human health and disease." (PMID 39453476, 2024).
cardiovascular disease (1 paper, 2025). "Moreover, emerging evidence suggests that DDX41 could be relevant in the regulation of metabolic and cardiovascular diseases, warranting further investigation into its broader clinical implications." (PMID 39158380, 2025). "Depletion of MEF2A leads to R‐loop accumulation and DDX41‐cGAS‐STING‐dependent inflammatory responses, highlighting a potential link between DDX41 and cardiovascular diseases." (PMID 39158380, 2025). "Overall, many lines of evidence highlight DDX41 as an upstream sensor of the cGAS‐STING pathway, implicating its relevance in cGAS‐STING‐dependent regulation of metabolic and cardiovascular diseases." (PMID 39158380, 2025).
haematological neoplasms (1 paper, 2022). "However, the difference in median age between the two MDS subgroups was not significant, which may indicate that patients with germline TET2 mutations need a long incubation period to develop MDS or other haematological tumors, such as the germline DDX41 mutation in haematological neoplasms." (PMID 35279121, 2022).
hematological tumors (1 paper, 2024). "The presence of germline mutations in DDX41 or CEBPA could inform clinicians about the relative risks of developing hematological tumors, the possible age at onset and the prognosis of the possible disease." (PMID 39118233, 2024).